SAPCD2 (suppressor APC domain containing 2)
Diseases named in the same sentence as SAPCD2 in open-access papers (continued):
Sharing a sentence is not in itself a finding about the gene and the disease.
prostate carcinoma (2 papers, 2021 to 2023). A carcinoma that arises from epithelial cells of the prostate gland. "Suppressor APC domain containing neuroblastoma (SAPCD2), has been reported to regulate Yap/Taz, MAPK, and mTOR signaling in various cancers, including colorectal and prostate cancer." (PMID 37705968, 2023).
cyst (1 paper, 2022). A sac-like closed membranous structure that may be empty or contain fluid or amorphous material. "Another polarity protein affecting LGN cortical recruitment is the suppressor APC domain containing 2 (SAPCD2), that has been shown to interact with Gαi/LGN complexes to orchestrate mitotic spindle orientation in MDCK cyst and in mouse retina." (PMID 35356279, 2022).
dermatofibrosarcoma protuberans (1 paper, 2020). Dermatofibrosarcoma protuberans (DFSP) is a rare infiltrating soft tissue sarcoma, generally of low grade malignancy, arising from the dermis of the skin and characteristically associated with a specific chromosomal translocation t(17;22). "The basic information of 48 patients with dermatofibrosarcoma protuberans for SAPCD2 immunohistochemical staining analysis." (PMID 33384953, 2020).
fibroma (1 paper, 2020). A non-metastasizing neoplasm arising from the fibrous tissue. "The basic information of 54 patients with fibroma for SAPCD2 immunohistochemical staining analysis." (PMID 33384953, 2020).
ganglioneuroma (1 paper, 2022). A benign neuroblastic tumor of the sympathetic nervous system that occurs in childhood. "SAPCD2 was also found to be significantly highly expressed in NB in comparison to ganglioneuroma (GN), the benign representative of peripheral neuroblastic tumors, by analyzing a recent study which performed RNA-Seq on GN and NB samples." (PMID 35197448, 2022).
head and neck squamous cell carcinoma (1 paper, 2019). A squamous cell carcinoma that arises from any of the following anatomic sites: lip and oral cavity, nasal cavity, paranasal sinuses, pharynx, larynx, and salivary glands. "Using TCGA dataset, we noted that the expression of PXN‐AS1‐L is significantly positively associated with SAPCD2 (r = 0.572) in head and neck squamous cell carcinoma." (PMID 31173488, 2019).
lung carcinoma (1 paper, 2022). "However, whether this SNP results in loss of function or gain of function of SAPCD2 and its resulting impact on lung cancer progression has yet to be explored." (PMID 35517423, 2022).
prostate tumors (1 paper, 2021). "Compared to normal tissues, ARHGEF38, NETO2, GOLM1, and SAPCD2 were hypomethylated in prostate tumors, while PRSS21 was hypermethylated in prostate tumors compared, which may be the underlying mechanism for the abnormal expression of the five genes in PCa." (PMID 34540835, 2021).
cancer (15 papers, 2011 to 2024). A tumor composed of atypical neoplastic, often pleomorphic cells that invade other tissues. "The potential of SAPCD2 as a diagnostic marker and therapeutic target of cancers have also been explored and have shown great promise." (PMID 35517423, 2022). "As a novel oncogenic factor, the potential of developing SAPCD2-based diagnostic and therapeutic tools will certainly be an important direction in the field of cancer research." (PMID 35517423, 2022). "Several studies have shown that the expression of SAPCD2 in G1 and M phases is higher than that during S and G2 phases, and cell cycle dysregulation is known to be associated with cancer progression." (PMID 32055236, 2020). "Aberrant expression of SAPCD2 has been widely reported to be implicated in the progression and metastasis in multiple cancer types." (PMID 33384953, 2020). "APOD, ACTA2, PDK4 and SAPCD2 have all been linked to the development of cancer in several studies." (PMID 38436027, 2024). "As an illustration, this revealed that important neighboring genes of the cancer gene SAPCD2 are enriched for other drivers, suggesting that PPI between these genes are important for the classification." (PMID 37189058, 2023). "Previous reports revealed that SAPCD2 is highly expressed in various cancers and is highly involved in the malignant transformation of cancer cells." (PMID 37508549, 2023). "Accumulating studies have shown an elevated expression level of SAPCD2 in a number of human cancers, such as colorectal cancer, fibrosarcoma, melanoma, and non-small cell lung cancer." (PMID 35197448, 2022). "The potential role of SAPCD2 in driving tumorigenic metastasis has been indicated in several types of human cancer." (PMID 35517423, 2022). "This therapeutic strategy of targeting SAPCD2 is certainly worth further pursuit in other cancer types in the future." (PMID 35517423, 2022). "CpG site-annotated genes such as SAPCD2 are critical in the progression of cancers and cardiovascular diseases." (PMID 35071775, 2022). "This study clearly demonstrates the ability of SAPCD2 to promote the oncogenic transformation of non-cancer cells and provides insight into the oncogenic mechanisms of SAPCD2 in general in cancers." (PMID 35517423, 2022). "The reliability of SAPCD2 as biomarker for cancer diagnosis and prognosis certainly need to be further evaluated in perspective clinical investigations." (PMID 35517423, 2022). "These preliminary investigations altogether demonstrated the potential of targeting SAPCD2 for cancer treatment." (PMID 35517423, 2022). "The investigation of SAPCD2 in pediatric cancers is still at preliminary stage overall, and future studies are needed to further characterize its role in pediatric cancers." (PMID 35517423, 2022). "Recent studies uncovered the emerging roles of SAPCD2 (suppressor anaphase-promoting complex domain containing 2) in several types of human cancer." (PMID 35197448, 2022). "Since its discovery, SAPCD2 has attracted great interest regarding its role in the context of cancer studies." (PMID 33384953, 2020). "Accumulating studies have reported that SAPCD2 is overexpressed in several types of human cancer, and that SAPCD2 overexpression promotes the proliferation, migration, and invasion of cancer cells by various mechanisms." (PMID 33384953, 2020). "Transcriptome analysis revealed that SAPCD2-knockdown led to alterations in genes involved in cell cycle, DNA replication, nuclear division, and spindle formation, which are all key cellular processes modulated by E2F signaling and often deregulated in cancer." (PMID 35197448, 2022). "In addition to its role in cancers, some evidence in favor of SAPCD2 contributing to other diseases has emerged." (PMID 35517423, 2022). "Indeed, the oncogenic function of SAPCD2 has been validated in in vitro and in vivo investigations and uncovered its potential as a valuable prognostic indicator of various types of cancers." (PMID 35517423, 2022).
cancer (continued). "Although the function of SAPCD2 in negatively regulating Wnt signaling appears to contradict its apparent role in tumorigenesis, other Wnt inhibitors have been found to be upregulated in cancers and function as oncogenic factors." (PMID 35517423, 2022). "The important role of SAPCD2 in tumorigenesis also suggests that targeting SAPCD2 may be an effective approach to treat cancers." (PMID 35517423, 2022). "The potential of SAPCD2 as a prognostic marker for cancer progression have also been investigated." (PMID 35517423, 2022). "SAPCD2 further promotes progression and metastasis in different human types of cancer by activating the Wnt/β-catenin, JAK/STAT, TGF-β, MAPK, and NF-κB signaling pathways, all of which have been reported to play crucial roles in cancer progression and metastasis." (PMID 33384953, 2020). "Several lines of evidence have reported that SAPCD2 may serve as a valuable prognostic marker in different types of cancer." (PMID 33384953, 2020). "miR-29a, a miRNA which functions as a tumor suppressor in multiple types of cancers 41, 42, is the first miRNA that was experimentally validated to bind to the SAPCD2 3'UTR and regulate SAPCD2 protein expression." (PMID 35517423, 2022). "Through a series of functional analyses (in vitro), we verified the pro-cancer abilities of NETO2 and SAPCD2, which provided a new approach for further study on the mechanism in PCa." (PMID 34540835, 2021).
tumor (12 papers, 2012 to 2026). "MR implicated 26 genes in EC risk; among these, ADORA2B and SAPCD2 were consistently overexpressed in tumors (external validation and RT-qPCR) yet higher tumor expression predicted longer survival." (PMID 42052492, 2026). "Our study also showed that enhanced expression of SAPCD2 was significantly associated with left tumor location, as well as increased cell migration, invasion, and proliferation." (PMID 32055236, 2020). "For the downregulated genes, Id1, Tor4a, Fam83d, Chst12, Fhod1, Sapcd2, and Gas2l3 are known as proliferative and metastatic oncogenes contributing to tumor progression." (PMID 40231790, 2025). "SAPCD2, as an oncogene, can promote cell proliferation and tumor development, potentially affecting pathways such as PI3K/Akt, MAPK, and Hippo, although its direct effect on immune checkpoints is not yet clear." (PMID 38515461, 2024). "They further found that high SAPCD2 expression level is correlated with poor tumor differentiation and advanced histological grade in both LUSC and LUAD, supporting a role in tumor differentiation." (PMID 35517423, 2022). "On the other hand, the interaction of miR-29a with SAPCD2 also indicates that SAPCD2 is among a downstream effector of miR-29a that mediates its tumor suppressive function." (PMID 35517423, 2022). "We also discovered the significant correlation of SAPCD2 transcript levels with the degrees of CIN in NB as well as some other tumor types." (PMID 35197448, 2022). "Although NETO2 and SAPCD2 have been reported to be involved in angiogenesis in different tumor types, the potential roles of these two genes in PCa were not elucidated." (PMID 34540835, 2021). "PXN‐AS1‐L promotes NPC cell proliferation, migration, and invasion in vitro, and NPC tumor growth in vivo via upregulating SAPCD2 expression." (PMID 31173488, 2019). "SAPCD2-knockdown resulted in a significant reduction in tumor size and weight." (PMID 35197448, 2022). "A recent study, however, suggested that SAPCD2 blocks Wnt/β-catenin signaling by interaction with Axin1 and in some contexts might function as a tumor suppressor." (PMID 35197448, 2022). "On the other hand, the expression of SAPCD2 in normal tumor-adjacent cells could potentially serve as an early indication of metastasis, but this is a speculative explanation and warrants further investigation through biological experiments." (PMID 35517423, 2022). "Collectively, these data revealed that SAPCD2 might have clinical implications in NB and perhaps other tumor types." (PMID 35197448, 2022). "Colony formation and flow cytometry for apoptosis analysis revealed that SAPCD2-knockdown could impair the growth and promote the apoptosis of tumor cells." (PMID 35197448, 2022). "The expression level of SAPCD2 in the tumor samples of 410 patients was associated with left tumor location (p = 0.018), but not with gender, age, TNM stage, or lymph node metastasis." (PMID 32055236, 2020). "Furthermore, SAPCD2 depletion resulted in stalled tumor enlargement in a mouse GC xenograft model." (PMID 35517423, 2022). "Interestingly, the authors reported that 30% of healthy tumor-adjacent tissues were also positive for SAPCD2 expression 24, raising the possibility that SAPCD2 may only be oncogenic when its expression level exceeds a certain threshold." (PMID 35517423, 2022). "The correlation analysis showed a significant positive link between SAPCD2 transcript levels and chromosome instability index (CIN) scores which were defined in a previous study and calculated from CNAs in tumor samples to evaluate the degree of CIN." (PMID 35197448, 2022). "Furthermore, depletion of SAPCD2 significantly reverses the roles of PXN‐AS1‐L in promoting NPC cell proliferation, migration, and invasion in vitro, and NPC tumor growth in vivo." (PMID 31173488, 2019).
tumor (continued). "Another study reported that SAPCD2 is overexpressed at both the mRNA and protein levels in CRC specimens compared to matched normal mucosa and that high SAPCD2 mRNA and protein expression levels are directly correlated with poor tumor differentiation and poor post-surgical prognosis of CRC patients." (PMID 35517423, 2022).
SAPCD2 also shares sentences with these, for which no sentence is quoted: glioblastoma (3 papers); renal cell carcinoma (3); astrocytomas (2); glioma (2); Bladder Cancer (1); brain glioma (1); cardiovascular diseases (1); colon adenocarcinoma (1); colon cancer (1); esophageal cancer (1); gastric tumor (1); Hepatitis B (1); lung adenocarcinoma (1); lymph node metastasis (1); malignant glioma (1); neuroblastic tumor (1); non-small cell lung carcinoma (1); prostate adenocarcinoma (1).